NDRG1 (N-myc downstream regulated 1)
Description:
Stress-responsive protein involved in hormone responses, cell growth, and differentiation. Acts as a tumor suppressor in many cell types. Has a role in cell trafficking, notably of the Schwann cell, and is necessary for the maintenance and development of the peripheral nerve myelin sheath. Required for vesicular recycling of CDH1 and TF. May also function in lipid trafficking. Protects cells from spindle disruption damage. Regulates microtubule dynamics and maintains euploidy.
Synonyms: DRG-1; RTP; CAP43; DRG1; TDD5; NDR1; CMT4D; GC4; HMSNL; NMSL; PROXY1; RIT42; TARG1
Tractability: Antibody: its Gene Ontology location is reachable by antibodies, with high confidence; UniProt places it where antibodies can reach, with medium confidence. PROTAC: ubiquitination databases record sites on it; its protein half-life has been measured.
Gene: Protein-coding gene on chromosome 8 (133,237,175 to 133,302,022, reverse strand). Ensembl gene ENSG00000104419.
Subcellular location: Cytoplasm, cytosol; Cytoplasm, cytoskeleton, microtubule organizing center, centrosome; Nucleus; Cell membrane
Subcellular location (Human Protein Atlas): Connecting piece; Cytosol; End piece; Mid piece; Principal piece; Calyx; Microtubules
Gene Ontology:
Molecular function: cadherin binding; gamma-tubulin binding; microtubule binding; nickel cation binding; protein binding; small GTPase binding
Biological process: cellular response to hypoxia; response to metal ion; signal transduction; negative regulation of cell population proliferation; peripheral nervous system myelin maintenance
Cellular component: adherens junction; centrosome; cytoplasm; cytosol; extracellular exosome; microtubule; nucleus; perinuclear region of cytoplasm; plasma membrane; recycling endosome membrane
Genetic constraint (gnomAD): Loss-of-function variants: 32 observed, 59.36 expected, observed/expected ratio (o/e) 0.54, 90% interval 0.41 to 0.72. The upper end of that interval is the gene's LOEUF score, 0.72, which puts it in group 2 of 6, group 1 being the genes least tolerant of losing a copy. Missense variants: 507 observed, 557.07 expected, observed/expected ratio (o/e) 0.91, 90% interval 0.85 to 0.98. Synonymous variants: 211 observed, 207.27 expected, observed/expected ratio (o/e) 1.02, 90% interval 0.91 to 1.14.
Cancer hallmarks: proliferative signalling (promotes); invasion and metastasis (suppresses); cell replicative immortality (suppresses); suppression of growth (promotes)
Homologues: Orthologues: chimpanzee NDRG1 (99% identical), macaque NDRG1 (99% identical), rabbit NDRG1 (96% identical), guinea pig NDRG1 (95% identical), mouse Ndrg1 (94% identical), rat Ndrg1 (93% identical), pig NDRG1 (93% identical), dog NDRG1 (81% identical), tropical clawed frog ndrg1 (75% identical), zebrafish ndrg1a (68% identical), zebrafish ndrg1b (55% identical), Drosophila melanogaster MESK2 (37% identical), and 3 more. Paralogues in human: NDRG3 (62% identical), NDRG4 (54% identical), NDRG2 (52% identical).
Diseases named in the same sentence as NDRG1 in open-access papers:
NDRG1 is named in the same sentence as 165 diseases in open-access papers, as found by Europe PMC text mining. Sharing a sentence is not in itself a finding about the gene and the disease. The quoted sentences say what the papers report.
breast carcinoma (97 papers, 2007 to 2026). "Immunohistochemical analysis of patient breast cancer tumors (n = 216) to assess NDRG1 expression profile revealed that high-NDRG1 expression was associated with cancer aggressiveness, shorter overall cancer survival, and breast cancer-specific survival." (PMID 40378957, 2025). "In breast cancer (BC), loss of NDRG1 mRNA expression is directly correlated with aberrant methylation and tumorigenesis." (PMID 40332138, 2025). "For example, SCD shows particularly high expression in HER2+ breast cancer and is closely associated with poor prognosis, while NDRG1 is highly expressed in aggressive breast cancer, where it acts as an oncogene promoting tumor growth and metastasis." (PMID 40923764, 2025). "The NDRG1 functions as a suppressor of metastasis and its expression has been associated with tumor progression and prognosis in various cancers, including breast cancer." (PMID 40862714, 2025). "López-Tejada and colleagues have observed similar results in their analysis of 83 samples from breast cancer patients, showing that high NDRG1 was associated with poor cumulative survival." (PMID 38611020, 2024). "Another study examining breast cancer found that silencing NDRG1 caused dysregulated lipid metabolism, leading to increased fatty acid conversion to neutral lipids and lipid droplets." (PMID 37345116, 2023). "The association between NDRG1 protein expression and aggressive features of breast cancer was analyzed using different statistical models based on the significance of the Q or I2 statistics, as mentioned in the method section." (PMID 37858101, 2023). "Simultaneously, a study of the underlying molecular mechanisms of NDRG1 is required to determine its role in breast cancer." (PMID 37842046, 2023). "Based on the findings of the meta-analysis, an increase in NDRG1 protein expression was associated with aggressive characteristics of breast cancer." (PMID 37858101, 2023). "The association between NDRG1 protein expression and breast cancer was assessed by analyzing a larger number of samples from multiple publications." (PMID 37858101, 2023). "In this study, NDRG1 was found to be an important regulator of lipid fate in breast cancer, where it was also associated with poor prognosis." (PMID 37345116, 2023). "A multivariate analysis with GOBO indicated that the higher NDRG1 gene expression is significantly associated with a higher hazard ratio (HR: ~2.5; p=0.01) in basal-like breast cancer patients than a lower expression (HR: ~0.5; p=0.43)." (PMID 36594086, 2023). "The results of the meta-analysis demonstrated a significant association between NDRG1 protein expression and the lymph node and Her2 statuses of breast cancer." (PMID 37858101, 2023). "The systematic review and meta-analysis demonstrated that NDRG1 protein expression were associated with breast cancer progression." (PMID 37858101, 2023). "Until now, NDRG1 has been implicated in divergent processes in breast cancer, complicating the interpretation of its function." (PMID 35459269, 2022). "In contrast, high levels of NDRG1 has been associated with poor prognosis in breast cancer and NDRG1 is a biomarker for aggressive breast cancer, suggesting a oncogenic role in breast cancer." (PMID 36213122, 2022). "Genetic or pharmacological targeting of CoREST emulated TBX2 loss, inducing NDRG1 expression and abolishing breast cancer growth in vitro and in vivo." (PMID 35687133, 2022). "We showed that, under hypoxic conditions, the expression of UCA1 was increased in MCF-7 breast cancer cells, and this overexpression was associated with significantly increased expression of Ca-IX and NDRG1, which are known as markers of hypoxia." (PMID 34054950, 2021). "Some studies have confirmed the downregulation of NDRG1 caused by DNA methylation of CpG islands of its promoter in breast cancer, prostate cancer cells and pancreatic cancer." (PMID 34616614, 2021).
breast carcinoma (continued). "NDRG1 showed the largest down-regulation in the cybrids with benign mitochondria and was associated with poor prognosis in a breast cancer clinical dataset." (PMID 32612361, 2020). "Nagai and colleagues also showed that high expression of NDRG1 was associated with aggressive breast cancer behaviors, including the advanced stage at presentation and high-grade tumors and that NDRG1 was independently associated with poor survival outcome." (PMID 33321961, 2020). "Two upregulated (EpCAM, FADD) and two downregulated (NDRG1, αB-crystallin) proteins were associated with the progression of breast cancer." (PMID 31443698, 2019). "For example, NDRG1 expression in prostate cancer cells was shown to be affected by androgens, whereas NDRG1 expression in breast cancer cells is mainly associated with estradiol." (PMID 31443698, 2019). "The association between NDRG1 and poor prognosis in breast cancer suggests it should play a more prominent role in patient risk assessment." (PMID 29898756, 2018). "In breast cancer, elevated NDRG1 expression has been linked to clinical outcomes, but its functional role in breast cancer physiology has remained unclear." (PMID 29898756, 2018). "Previous work has shown NDRG1 expression to be part of an angiogenesis-related gene signature associated with metastasis in breast cancer." (PMID 29898756, 2018). "Downregulation of NDRG1 mRNA has been associated with increased tumorigenesis in breast cancer." (PMID 40733287, 2025). "Indeed, further studies are needed to elucidate the underlying mechanisms through which NDRG1 exerts its metabolic switch activity in breast cancer." (PMID 38983911, 2024). "This means that more NDRG1 protein expression is linked to a less aggressive type of breast cancer." (PMID 37858101, 2023). "Therefore, the present study adopts a systematic review and meta-analysis approach to synthesize the evidence and investigate the association between NDRG1 expression and the aggressive characteristics of breast cancer." (PMID 37858101, 2023). "Therefore, the present study utilized a systematic review and meta-analysis approach to synthesize the association between NDRG1 protein expression and the aggressive characteristics of breast cancer." (PMID 37858101, 2023). "Additionally, Kaplan–Meier meta-analyses showed that a high expression of NDRG1 mRNA level is specifically significantly associated with RFS in breast cancer patients with high YAP1 expression." (PMID 35459269, 2022). "NDRG1 overexpression enhances aerobic glycolysis and imparts growth advantages to cells, induces the expression of hypoxia-associated genes, and causes lipid metabolism dysfunction in breast cancer." (PMID 32025371, 2020). "A large meta-analysis was conducted examining the association between NDRG1 expression and recurrence-free survival in 23 publicly available breast cancer mRNA expression data sets representing 3554 subjects with breast cancer assessed as a single aggregated cohort." (PMID 29898756, 2018). "In our current study, the MSP results demonstrated that the status of methylation had a greater frequency in 87 breast tumors compared with corresponding normal tissues (P < 0.001), which showed that NDRG1 promoter methylation status was relative to the genetic risk variants for breast cancer." (PMID 23899187, 2013). "Thus, NDRG1 may be associated with breast cancers with marked glycolytic and angiogenic gene expression at the mRNA level." (PMID 40378957, 2025). "Similarly, in our own study of patients with inflammatory breast cancer, a rare and highly aggressive variant of breast cancer, we found that tumors with high NDRG1 expression were associated with worse overall and disease-specific survival compared with NDRG1-low tumors." (PMID 38611020, 2024). "A large meta-analysis examined the relationship between NDRG1 expression and recurrence-free survival in 23 publicly available breast cancer mRNA expression datasets, assessing 3554 patients with breast cancer." (PMID 40378957, 2025).
breast carcinoma (continued). "Kaplan-Meier analysis suggested that patients with breast cancer having positive NDRG1 expression had a markedly worse prognosis than those with NDRG1 negatively expressed." (PMID 40378957, 2025). "In vivo studies using NDRG1-knockdown breast cancer cells (SUM149 and MDA-IBC3) demonstrated significantly reduced tumor volumes and inhibited brain metastasis versus control." (PMID 40378957, 2025). "In contrast, there is evidence of NDRG1 being highly expressed in brain metastatic breast cancer and n breast cancer, the latter being a rare tumor that occurs after tumor cells embolize and block lymphatic vessels." (PMID 40378957, 2025). "There have also been reports of NDRG1 playing a potential pro-oncogenic role in esophageal cancer, breast cancer, osteosarcoma, bladder cancer, hepatocellular cancer, gastric cancer, and non-small cell lung cancer." (PMID 40378957, 2025). "Depleting TBX2, Sp1 or CoREST members resulted in the de-repression of NDRG1 which was accompanied by reduced breast cancer cell viability and colony-forming ability." (PMID 39912718, 2025). "Further examination of an independent cohort of 295 patients with breast cancer, where metastasis was recorded, evaluated the relationship between metastasis and NDRG1 mRNA expression." (PMID 40378957, 2025). "In contrast, there is a positive correlation between NDRG1 and genes related to angiogenesis, glycolysis, hypoxia, and basal cell lineage in breast cancer." (PMID 40378957, 2025). "NDRG1 was amplified in 33% of metastatic tumors in the Metastatic Breast Cancer dataset relative to 17% of primary breast tumors from the TCGA invasive breast cancer dataset." (PMID 40378957, 2025). "The role of NDRG1 in breast cancer phenotype remains complex, as reports suggest both pro- and anti-oncogenic roles." (PMID 40378957, 2025). "We investigated N‐myc downregulated gene‐1 (NDRG1) as a clinically relevant biomarker in breast cancer brain metastasis patients." (PMID 40530439, 2024). "Specifically, we observed NDRG1 amplification in 23% of breast cancer samples, whereas NDRG2 was amplified in 0.9% cases, NDRG3 in 2.5% and NDRG4 in 0.3%." (PMID 38611020, 2024). "In support of these patient-sample analyses, others have described NDRG1 as having pro-oncogenic functions in models of aggressive breast cancer." (PMID 38611020, 2024). "Our analysis revealed that NDRG1 is among the most frequently amplified genes in this cohort of breast cancer patients." (PMID 38611020, 2024). "Silencing SGK1, a kinase known to regulate NDRG1 phosphorylation, was also found to inhibit NDRG1 expression and increase breast cancer cell migration and invasion in vitro." (PMID 38611020, 2024). "Our findings suggest NDRG1 expression and subcellular localisation are clinically relevant biomarkers for poor prognosis in breast cancer and breast cancer brain metastasis." (PMID 40530439, 2024). "First, NDRG1 seems to have a dualistic function in breast cancer, acting as both a tumor/metastasis promoter and suppressor, but mounting evidence supports a pro-metastasis role in aggressive breast cancers." (PMID 38611020, 2024). "Here, we found that NDRG1 is an independent prognostic marker of poor outcome in breast cancer (BC)." (PMID 39736699, 2024). "Our work also highlights a novel facet of NDRG1 in modulating glycolytic and mitochondrial respiration of breast cancer cells." (PMID 38983911, 2024). "In summary, we have demonstrated that mitochondrially targeted iron chelators, mitoDFO and mitoDFX, upregulate NDRG1 expression and induce Thr346 phosphorylation via the GSK3α/β kinase in breast cancer cells." (PMID 38983911, 2024). "One of those two studies has found that breast cancer patients with NDRG1-negative tumors had worse disease-free survival than patients with NDRG1-positive tumors." (PMID 38611020, 2024).
breast carcinoma (continued). "Many studies have demonstrated the anti-oncogenic and anti-metastatic activities of N-myc downstream-regulated gene 1 (NDRG1) in a variety of aggressive solid tumors, including pancreatic cancer, breast cancer, colon cancer, and prostate cancer." (PMID 38815861, 2024). "In the current study, we showed that overexpression of full-length NDRG1 suppressed invasion in ER+ breast cancer." (PMID 38983911, 2024). "To determine the role of NDRG1 overexpression in malignant breast cancer cells and its impact on cell proliferation, we generated clones stably overexpressing (OE) full-length NDRG1 (isoform 34,945) in both malignant cell lines." (PMID 38983911, 2024). "In this study, we evaluated the ability of these modified chelators to induce NDRG1 and the role of NDRG1 in breast cancer." (PMID 38983911, 2024). "On the other hand, both truncated NDRG1 forms exhibited slightly higher basal proliferation rates in MDA-MB-231 breast cancer cells." (PMID 38983911, 2024). "We further report that NDRG1 KO increased the sensitivity of breast cancer cells to mitoDFX treatment." (PMID 38983911, 2024). "Although NDRG1 was first considered to suppress metastasis in breast cancer, evidence is mounting to indicate that NDRG1 has pro-oncogenic and pro-metastatic effects in breast cancer." (PMID 38611020, 2024). "Collectively, these findings show that NDRG1 is correlated with aggressiveness and poor survival outcomes in patients with breast cancer." (PMID 38611020, 2024). "These in vitro and in vivo findings provide strong evidence that NDRG1 plays a significant role in promoting the metastasis of aggressive breast cancer cells." (PMID 38611020, 2024). "Bandyopadhyay and colleagues were the first to show that NDRG1 overexpression in breast cancer cell lines inhibited invasion in vitro, and that NDRG1 expression was regulated by PTEN." (PMID 38611020, 2024). "For the first time, we have shown that mitochondrially targeted iron chelators, mitoDFO and mitoDFX, upregulate NDRG1 at both mRNA and protein levels in breast cancer cells." (PMID 38983911, 2024). "NDRG1 was highly expressed in breast‐to‐brain metastases, as well as in high‐grade primary breast cancers." (PMID 40530439, 2024). "The increased expression of NDRG1 upon progesterone treatment in breast cancer tissue samples and cell lines confirms the progestogenic- and stress-mediated genomic regulation of NDRG1." (PMID 37395734, 2023). "A meta-analysis of NDRG1 expression using data from genomic databases revealed that an altered lipid metabolic phenotype in breast cancer cells contributes to the aggressiveness of the disease." (PMID 37858101, 2023). "In public datasets, NDRG1 gene expression has been found higher in the aggressive breast cancer subtypes basal-like, HER2+, and TNBC, which was correlated with poorer overall survival 9,17,18,26." (PMID 36594086, 2023). "For instance, high expression of NDRG1 in breast cancer cells was found to increase brain metastasis formation and was correlated with worse clinical outcomes and reduced survival." (PMID 37345116, 2023). "NDRG1 can reduce activity of some kinases, thus reducing invasion and migratory potential of breast cancer cells." (PMID 37249826, 2023). "Conversely, NDRG1 expression directly suppressed breast cancer bone metastasis in vivo, and was found to be correlated with improved relapse-free survival in Wnt-negative patient specimens." (PMID 37345116, 2023). "This would allow for a more refined conclusion regarding the implications of NDRG1 protein expression levels in breast cancer aggressiveness and prognosis." (PMID 37858101, 2023). "The role of NDRG1 in breast cancer remains controversial, with some studies showing a tumor-suppressive effect, while others suggest that NDRG1 promotes breast cancer progression." (PMID 37345116, 2023).